EPHB1 (EPH receptor B1)
Diseases named in the same sentence as EPHB1 in open-access papers (continued):
Sharing a sentence is not in itself a finding about the gene and the disease.
colorectal cancer (7 papers, 2018 to 2024). A primary or metastatic malignant neoplasm that affects the colon or rectum. "From these, 15 recurring EPHB1 mutations were stably expressed in colorectal cancer followed by confocal microscopy based in vitro compartmentalisation assays and phospho-proteome analysis." (PMID 38102712, 2023). "In addition, a reduced level of EPHB1 in colorectal cancer cells was associated with increased invasive potential in one study." (PMID 30738427, 2019). "Underexpression of the EphB1 protein is significantly associated with tumor progression in gastric carcinomas and higher invasiveness of colorectal cancer cells, suggesting a tumor-suppressive role of the protein and possible implication in the beneficial effects of metformin." (PMID 30545422, 2018). "Analyzing single-cell sequencing data of colorectal cancer revealed endothelial cells as a prominent cluster, expressing the EphB1 gene significantly." (PMID 38811954, 2024). "Specifically, EphB1 has been found to be down-regulated in gastric cancer, renal cell carcinomas and colorectal cancer." (PMID 38811954, 2024). "Overall, these results indicate that colorectal cancer is distinct from other cancer types in displaying higher expression of EphrinB2 and its receptors EphB1, EphB2, EphB3, and EphB4." (PMID 31545551, 2019). "To evaluate the effects of EphB2 depletion, we selected the SW620 colorectal carcinoma cell line, which contains abundant EphB2, whereas EphB1, EphB3, and EphB4 are undetectable and EphA4 is detected at low levels." (PMID 31545551, 2019). "The differentially methylated regions revealed the gene EPHB1, whose under‐expression leads to gastric carcinoma and invasion of colorectal cancer cells, and SERP2, which is positively correlated with body mass index (BMI) and abnormal glucose tolerance as well as colorectal cancer." (PMID 33392433, 2020). "The HT‐29 colorectal carcinoma cell line, which needs EphrinB2 to survive, contains abundant EphB4 but not EphB1, EphB2, EphB3, or EphA4 proteins, as observed previously." (PMID 31545551, 2019). "We examined the expression of EphrinB2 ligand and the EphrinB2 signaling receptors (EphB1, EphB2, EphB3, EphB4, and EphA4) in colorectal carcinoma." (PMID 31545551, 2019).
lung carcinoma (7 papers, 2020 to 2025). "Dormancy and reactivation of lung cancer cells following cisplatin treatment has also been shown to be dependent on a Sox2/Nanog regulated mechanism relying on sequential cis and trans ephrin type-B receptor 1 (EphB1)-mediated signaling." (PMID 37207158, 2023). "Expression of EphB1 showed an increase in dormant state and a decrease in reactivated lung cancer cell." (PMID 36402751, 2022). "In order to evaluate the expressions p-EphB1 in lung cancer patients, we collected cancer biopsies from patients who underwent surgery after neoadjuvant chemotherapy and brain metastatic samples of lung cancer patients." (PMID 36402751, 2022). "EphB1 cis- and trans- signalings function in the dormant and reactivated state of lung cancer cells respectively." (PMID 36402751, 2022). "Ligand-independent EphB1 promoted entry of lung cancer cells into dormancy through activating p-p38 and downregulating E-cadherin." (PMID 36402751, 2022). "The immunohistochemical staining of p-EphB1 revealed that lung cancer biopsies after cisplatin treatment showed decreased p-EphB1." (PMID 36402751, 2022). "We then measured EphB1 expression in lung cancer cells in dormant and reactivated cancer cells by western blot." (PMID 36402751, 2022). "In the dormant EMT cells which showed disrupted cell-cell contacts, ligand-independent EphB1 promoted entry of lung cancer cells into dormancy through activating p-p38 and downregulating E-cadherin." (PMID 36402751, 2022). "It demonstrated that phosphorylation of EphB1 reduces migration and invasion of lung cancer cells, whereas the ligand-independent EphB1 promotes migration and invasion of lung cancer cells." (PMID 32368295, 2020). "In this study, we found that ligand-independent EphB1 promoted lung cancer cell mobility and invasion." (PMID 32368295, 2020). "To investigate the roles of EphB1 in the migration and mobility of lung cancer cell, we transfected EphB1 expression vector into H460 cells or EphB1 siRNA into A549 cells." (PMID 32368295, 2020). "Here, we studied the ligand mediated trans-forward EphB1 signaling and ligand-independent cis-attenuation signaling contribute to the migration and invasion of lung cancer cells." (PMID 32368295, 2020). "On the contrast, Ephrin-B2, a transmembrane ligand for EphB1 forward signaling, inhibited migration and invasion of lung cancer cells." (PMID 32368295, 2020). "The transwell assay revealed that EphB1 promoted the migration and invasion of lung cancer cells and knockdown of EphB1 resulted in reduced migration and invasion in A549 cells." (PMID 32368295, 2020). "To investigate the relationship between EphB1 and lung cancer, we analyzed EphB1 expression in lung samples from cancer patients." (PMID 32368295, 2020). "While the role of specific EPH receptor mutations has been functionally studied in certain tumour types, like EPHA3 in lung cancer, the role of EPHB1 somatic mutations had not been studied to date." (PMID 38102712, 2023). "The brain metastatic loci of lung cancer showed increased p-EphB1." (PMID 36402751, 2022). "However, the phosphorylation of EphB1 showed dynamic expression, whose expression was downregulated in dormant lung cancer cells and recovered in reactivated lung cancer cells after chemotherapy." (PMID 36402751, 2022). "EphB1 expression in lung biopsies was correlated with poor patient survival in lung cancer." (PMID 32368295, 2020). "The roles of EphB1 and its phosphorylation signaling in lung cancer remain to be elucidated." (PMID 32368295, 2020). "Overexpression of EphB1 promoted the migration and invasion of lung cancer cells." (PMID 32368295, 2020). "Higher EphB1 expression was correlated with poor patient survival in lung cancer." (PMID 32368295, 2020). "However, the ligand induced EphB1 phosphorylation inhibited lung cancer mobility and invasion." (PMID 32368295, 2020).
lung carcinoma (continued). "For example, SMAD2 activated by TGF-β signaling upregulates the expression of EPHB1, which further promotes epithelial–mesenchymal transition (EMT) by elevating CDH2 expression in lung cancer." (PMID 40548257, 2025). "In our study, phosphorylated EphB1 and non-phosphorylated EphB1 conferred different functions in the dormancy and reactivation of lung cancer cells after treatment of cisplatin." (PMID 36402751, 2022). "In the old lung cancer group, there were genes significantly concurrent with actionable driver genes (CDKN2A, NF1): FAT1, LRP1B, ARID2 with CDKN2A; EPHB1 with NF1, and genes significantly exclusive with actionable driver genes (EGFR, KRAS): MLL2, STK11, KRAS with EGFR." (PMID 35096611, 2021). "Consistent with results obtained from public database, the higher EphB1 expression was detected in metastatic lung cancer samples than in non-metastatic lung cancer samples." (PMID 32368295, 2020). "EphB1 has been found to be upregulated in lung cancer biopsies compared to non-cancer controls." (PMID 36402751, 2022). "The overexpression of EphB1 did not affect the lung cancer cell growth." (PMID 32368295, 2020). "To investigate the mechanism of how EphB1 overexpression promotes the migration and invasion of lung cancer cells, we compared the expression of EMT related molecules between cells with or without forced expression of EphB1." (PMID 32368295, 2020).
breast carcinoma (5 papers, 2010 to 2025). "Of note, Márquez-Ortiz described an ephrin-dependent (EFNB1/EPHB1) mechanism underlying an IL13RA2 function in breast cancer brain metastasis." (PMID 40663259, 2025). "Together, association studies, early expression changes in carcinogenesis and the regulation of cell adhesion suggest the involvement of EPHB1 in risk of breast cancer." (PMID 21124932, 2010). "In this analysis, the rs3732568 variant in the ephrin type-B receptor 1 (EPHB1) locus was found to be associated with risk of breast cancer: OR = 0.79, 95% CI: 0.63–0.98; Ptrend = 0.031." (PMID 21124932, 2010). "Association between genetic variation in EPHB1 and risk of breast cancer in Poland." (PMID 21124932, 2010). "EPHB1 showed the highest relative mRNA expression in the breast cancer samples and EPHA2 the lowest." (PMID 26870995, 2016).
ovarian carcinoma (4 papers, 2006 to 2025). A malignant neoplasm originating from the surface ovarian epithelium. "In some cases it was shown only decreased expression (LOC285205, EPHB1 and RBSP3 (CTDSPL)) and in other cases loss of heterozygosity and copy number changes (CGGBP1 and RBSP3 (CTDSPL)) in ovarian cancer." (PMID 23202957, 2012). "To exemplify the power of NeDRex to extract biologically meaningful pathways from starting seeds, we used the ovarian cancer (OC) associated genes from NeDRexDB (AKT1, ALPK2, CDH1, CTNNB1, EPHB1, OPCML, PIK3CA, PRKN) and constructed disease module using the MuST algorithm." (PMID 34824199, 2021). "Initially, the expression of 20 different Eph and ephrin genes (EphA1-A8, EphB1-4 and 6, ephrin A1-5 and ephrin B1-2) were screened by quantitative real time reverse transcriptase polymerase chain reaction (Q-PCR) on two normal ovaries and ten ovarian cancer specimens." (PMID 16737551, 2006).
gastric carcinoma (3 papers, 2012 to 2018). A carcinoma that arises from epithelial cells of the stomach. "The reduced expression of EphB1 has been linked with invasion and metastasis in both colorectal and gastric carcinomas, while blocking EphB1 forward signalling may have a clinical benefit in relieving bone cancer pain." (PMID 23627399, 2013).
melanoma (3 papers, 2019 to 2023). A malignant, usually aggressive tumor composed of atypical, neoplastic melanocytes. "R682C is associated with endometrioid carcinoma, adult T cell lymphoma-leukemia, and malignant melanoma, but the role of EphB1 in these cancer types has not been well studied." (PMID 37527777, 2023).
brain tumors (2 papers, 2017 to 2024). "Moreover, it will be important to investigate whether EphB1 mutations widely exist in brain tumor patients and the effect of these mutations on tumorigenesis." (PMID 28194092, 2017). "First, appropriate studies are crucial to decipher the paradoxes of EphB1/ephrins signaling in different cellular contexts during the development of a variety of brain tumors." (PMID 28194092, 2017). "The action mechanism of EphB1/ephrins signaling appears to be complex in normal central nervous tissue and brain tumors." (PMID 28194092, 2017). "In conclusion, the roles of EphB1/ephrins signaling in brain tumors are only beginning to be explored, and further studies will generate more comprehensive data." (PMID 28194092, 2017). "By now, our understanding on the complicated functions of EphB1/ephrins signaling in brain tumors is still limited, and more studies are urgently needed to resolve the confusing and controversial events." (PMID 28194092, 2017). "This review focuses on EphB1 that has both tumor-suppressing and -promoting roles in some brain tumors." (PMID 28194092, 2017). "In this review, we focus on the roles of EphB1/ephrins signaling in malignant brain tumors." (PMID 28194092, 2017). "It is also promising to investigate whether the immune response initiated by EphB1/ephrin signaling is involved in tumorigenicity of brain tumors." (PMID 28194092, 2017). "Understanding the intracellular mechanisms of EphB1 in tumorigenesis and metastasis of brain tumors might provide a foundation for the development of EphB1-targeted therapies." (PMID 28194092, 2017). "Furthermore, it is essential to explore the correlation of EphB1 expression levels with the clinical outcomes of various brain tumor types in order to determine whether EphB1 is a favorable prognostic predictor for patients." (PMID 28194092, 2017).
Cognitive impairment (2 papers, 2022 to 2024). Abnormal cognition is characterized by deficits in thinking, reasoning, or remembering. "Genes involved in the cognitive impairment MAG, GDF15, GPR176, and EPHB1 (upregulated), BCL11B, GIMAP7, and ACOD1 (downregulated) were differentially expressed." (PMID 38755198, 2024).
colon adenocarcinoma (2 papers, 2018 to 2023). "When considering only EPHB1, the most frequent altered tumour types included uterine corpus endometrial carcinoma, lung, and colon adenocarcinoma with mutation frequencies of 10.9%, 6.3% and 6%, respectively." (PMID 38102712, 2023). "In the TCGA dataset, EPHB1 C61Y was found in a colon adenocarcinoma and, aligned in the same position of the protein consensus sequence, the corresponding EPHA2 C70R mutant was found in a renal papillary cell carcinoma." (PMID 38102712, 2023). "We identified loss-of-function uORF mutations in EPHB1 in two samples derived from breast and colon cancer, and in MAP2K6 in a sample of colon adenocarcinoma." (PMID 29402903, 2018).
colon cancer (2 papers, 2018 to 2019). "Also, analysis of paired normal colon tissue and colon cancer (n = 26) showed that mRNA levels of EphB2, EphB3, EphB4, and EphA4 are significantly lower in the normal tissue than in the adjacent cancer, whereas levels of EphrinB2 and EphB1 are similar." (PMID 31545551, 2019).
diabetes (2 papers, 2021 to 2022). "In the context of diabetes, EphB1 seems to be more involved in the maintenance of pain than in its development." (PMID 36231105, 2022). "In diabetic neuropathic pain, blocking of spinal EphB1 reduced microglia activation along with inflammatory mediator production and subsequently reduced late diabetes-induced allodynia." (PMID 34630039, 2021). "Furthermore, in the STZ-induced diabetes model, while increased phosphorylation of EphB1 expressed by glia positively correlates with gliosis and neuropathic pain, the blockade of EphB1 leads to decreased astrocytosis and cytokine release." (PMID 36231105, 2022).
glioblastoma (2 papers, 2017 to 2026). The most malignant astrocytic tumor (WHO grade IV). "Moreover, survival analysis indicated that glioblastoma multiforme (GBM) patients with higher EphB1 expression level show longer survival rates." (PMID 28194092, 2017).
meningioma (2 papers, 2024 to 2025). A generally slow growing tumor attached to the dura mater. "Moreover, EPHA2 and EPHB1 are overexpressed in neurofibromatosis type 2 gene (NF2) deficient meningiomas, and their pharmaceutical targeting with Dasatinib favors patients’ prognosis." (PMID 38612645, 2024). "In meningiomas, aberrant activation of EphA2 and EphB1 promotes proliferation through engagement with mTOR and ERBB3 signaling pathways." (PMID 41200151, 2025). "In NF2-null meningioma cell lines, kinome profiling revealed activation of Eph receptor tyrosine kinases (EphA2, EphB1), c-KIT, and the Src/SFK pathway, targets of the FDA-approved kinase inhibitor Dasatinib." (PMID 41200151, 2025).
oligodendroglioma (2 papers, 2017 to 2021). A well-differentiated (WHO grade II), diffusely infiltrating neuroglial tumor, typically located in the cerebral hemispheres. "EPHB1 seemed to have a beneficial influence, since its expression correlated with longer patient OS and was upregulated in oligodendrogliomas, which notably have a more favorable outcome compared to other infiltrating glioma tumors." (PMID 34445116, 2021). "In a large study that included 171 tumor samples (29 astrocytomas, 82 GBM, 49 oligodendrogliomas, 11 oligoastrocytomas) and 24 non-tumorous brain specimens from epileptogenic patients, EPHB1, B2, B3, B4, and B6 expression was assessed by quantitative real-time RT-PCR." (PMID 34445116, 2021).
prostate carcinoma (2 papers, 2025). A carcinoma that arises from epithelial cells of the prostate gland. "A Co-IP experiment was performed to detect the relationship between EPHB1 and GSK3B protein, which has been reported to be involved in apoptosis, migration, and invasion in prostate cancer, and the results confirmed the interaction between EPHB1 and GSK3B protein." (PMID 40548257, 2025). "We also examined the expression of other EphB receptor family members (EphB1, EphB2, EphB3) with no change in normal and prostate cancer." (PMID 40044981, 2025).
Stroke (2 papers, 2016 to 2023). Sudden impairment of blood flow to a part of the brain due to occlusion or rupture of an artery to the brain. "In stroke, ephrin-A5 upregulation in reactive astrocytes is associated with a significant increase in the phosphorylation of EphA receptors in peri-infarct tissue and EphB1 levels are increased during axonal sprouting following stroke." (PMID 26928051, 2016).
acute myelogenous leukemia (1 paper, 2017). "A recent study demonstrated an inverse correlation between the expression of EphB1 transcripts and EphB1 promoter methylation in pediatric acute myelogenous leukemia." (PMID 28194092, 2017).
amyotrophic lateral sclerosis (1 paper, 2017). Amyotrophic lateral sclerosis (ALS) is a neurodegenerative disease characterized by progressive muscular paralysis reflecting degeneration of motor neurons in the primary motor cortex, corticospinal tracts, brainstem and spinal cord. "Finally, we demonstrate that the EphB1–ephrin-B1 pathway is disrupted in human stem cell derived astrocyte and mouse models of amyotrophic lateral sclerosis (ALS)." (PMID 29079839, 2017). "Here the authors identify a pathway via neuronal EphB1 that induces neuroprotective signalling in astrocytes through ephrin-B1 mediated STAT3 activation, which is impaired in models of amyotrophic lateral sclerosis." (PMID 29079839, 2017).
bleeding disorder (1 paper, 2022). "EPHB1 is expressed in platelets and was suggested to be involved in clot stability, but it has never been linked to a bleeding disorder." (PMID 36231035, 2022).
cardiac hypertrophy (1 paper, 2022). "In detail, we identified extensive dysregulation of the Eph receptor EPHB1 in human cardiac hypertrophy, highlighting the importance of this pathway for future therapeutic interventions." (PMID 39195989, 2022). "Downregulation of EPHB1 in cardiac hypertrophy would imply that EFNB2–EPHB1 interactions might inhibit the hypertrophic response." (PMID 39195989, 2022).
cervical cancer (1 paper, 2022). A primary or metastatic malignant neoplasm involving the cervix. "To further validate the observation, we performed RT-PCR to detect the transcripts encoding EPHB1 and its isoform EPHA6, well known transcripts regulating axonogenesis and neuronal growth in exosomes of cervical cancer cells." (PMID 35148692, 2022). "Interestingly, our RT-PCR analysis showed presence of EPHB1 in the exosomal cargo of HPV-positive cervical cancer cells." (PMID 35148692, 2022).
dependence (1 paper, 2008). "This study, using EphB1 receptor knockout (EphB1-/-) and down (EphB1+/-) mice, demonstrates, for the first time, that the subtype EphB1 receptor is required for the development of neuropathic hyperalgesia and morphine dependence." (PMID 19025592, 2008).
glaucoma (1 paper, 2023). Increased pressure in the eyeball due to obstruction of the outflow of aqueous humor. "It has been shown that activation of the ephrinB1/EphB1 positive signaling pathway induces TNF-α production and may play an important role in the apoptosis of retinal ganglion cells in glaucoma." (PMID 37501725, 2023).
injury (1 paper, 2008). Damage inflicted on the body as the direct or indirect result of an external force, with or without disruption of structural continuity. "In addition, we have noticed that a small proportion of EphB1-/- and EphB1+/- mice (~10%) exhibit hyperalgesia after nerve injury or spinal administration of ephrinB1-Fc." (PMID 19025592, 2008).